RNU6-615P (RNA, U6 small nuclear 615, pseudogene)
Gene: Small nuclear RNA gene on chromosome 4 (83,003,412 to 83,003,517, forward strand). Ensembl gene ENSG00000251874.
Homologues: Orthologues: chimpanzee U6 (99% identical), dog U6 (61% identical), guinea pig U6 (59% identical), mouse Gm22708 (57% identical). Paralogues in human: RNU6-454P (72% identical), RNU6-43P (71% identical), RNU6-884P (70% identical), RNU6-944P (70% identical), RNU6-87P (69% identical), RNU6-1094P (68% identical), RNU6-1216P (68% identical), RNU6-1243P (68% identical), RNU6-183P (68% identical), RNU6-233P (68% identical), RNU6-398P (68% identical), RNU6-445P (68% identical), and 1286 more.